MIR548S (microRNA 548s)
Synonyms: hsa-mir-548s
Gene: MicroRNA gene on chromosome 2 (11,767,444 to 11,767,525, forward strand). Ensembl gene ENSG00000265056.
Homologues: Orthologues: chimpanzee MIR548S (100% identical). Paralogues in human: MIR548P (73% identical), MIR548F3 (72% identical), MIR548O2 (72% identical), MIR548AZ (71% identical), MIR548AH (70% identical), MIR548K (70% identical), MIR548F1 (68% identical), MIR548H3 (68% identical), MIR548X (68% identical), MIR548AA1 (67% identical), MIR548AJ1 (67% identical), MIR548AY (66% identical), and 13 more.